PGR (progesterone receptor)
Diseases named in the same sentence as PGR in open-access papers (continued):
Sharing a sentence is not in itself a finding about the gene and the disease.
breast cancer (continued). "GATA3 expression was also highly associated with estrogen receptor and progesterone receptor status (p = 0.0001) and tumor grade (p = 0.004) in breast carcinomas." (PMID 17078870, 2006). "The relationship between a higher body mass index (BMI) and the risk of ER+/PgR+ breast cancer has been studied previously." (PMID 15904529, 2005). "Loss of oestrogen or progesterone receptor expression was the first molecular feature recognised to associate with poor survival in breast cancer." (PMID 12618880, 2003). "Here, in the Breast Cancer-Anti-Progestin Prevention Study 1 (BC-APPS1; NCT02408770), we assessed whether progesterone receptor antagonism with ulipristal acetate for 12 weeks reduces surrogate markers of breast cancer risk in 24 premenopausal women." (PMID 41193807, 2025). "Furthermore, beyond pregnancy-related outcomes, rs4754732 has also been implicated in breast cancer, highlighting its broader significance in hormonal regulation and progesterone receptor function." (PMID 40004073, 2025). "Estrogens may contribute to breast cancer risk indirectly by induction of the progesterone receptor and thus amplifying progesterone signaling." (PMID 39522613, 2025). "Additionally, AKT1 has been linked to progestin resistance in endometrial and breast cancers by reducing progesterone receptor expression." (PMID 40028534, 2025). "Furthermore, this gene expression signature was linked to breast carcinogenesis and notably linked with progesterone receptor expression status in breast cancer, as validated in The Cancer Genome Atlas dataset using the R2 platform." (PMID 39062832, 2024). "Common risk factors associated with the prognosis of breast cancer, such as age, ethnicity, tumor size, histological differentiation grade, estrogen receptor (ER), progesterone receptor (PR), human epidermal growth factor receptor 2 (HER2) and Ki-67, have been well-recognized." (PMID 38525418, 2024). "Breast cancer patients with a positive Bcl-2 protein expression are considered to have a better prognosis, and Bcl-2 is significantly associated with several favorable prognostic factors such as tumor size, ER and progesterone receptor positivity." (PMID 38167446, 2024). "In agreement with a pattern recently reported in primary breast cancer, several genes from the highly intercorrelating gene cluster associated to hormone responsiveness (AR, PGR, ER signaling, ESR1, and FOXA1) emerged as interesting prognostic markers for MBC, both when expressed in PT and in DM." (PMID 38449790, 2023). "The expression of biomarkers, too, was consistent with human breast cancers resulting in a poor prognosis, with a gradual loss in ER, progesterone receptor, as well as integrin-β1 along with the persistent expression of cyclin-D1 and ErbB2/Neu (equivalent to human HER2)." (PMID 37297024, 2023). "Part of the reason that TNBCs have limited treatment options is that they are deficient in three traditional protein targets of breast cancer therapy—the estrogen receptor (ER); the progesterone receptor (PR); and the human epidermal growth factor receptor 2 (HER2)." (PMID 37760451, 2023). "In a study involving 535,941 breast cancer patients, the results indicated that a positive estrogen receptor status (RR = 0.93 and p = 0.014) and positive progesterone receptor status (RR = 0.86 and p < 0.001) were associated with a lower risk of developing BC-LuC." (PMID 38021219, 2023). "Of young adults with stage I-III estrogen receptor–positive or progesterone receptor–positive breast cancer, Medicaid expansion was associated with a net increase of 2.42 percentage points (95% confidence interval [CI] = 0.56 to 4.28 percentage points) in the percentage receiving endocrine therapy." (PMID 37707583, 2023).
breast cancer (continued). "On the other hand, in the ABCSG-18 study including 3,425 postmenopausal women with estrogen receptor-positive or progesterone receptor-positive early breast cancer, adjuvant denosumab therapy delayed the disease recurrence in postmenopausal patients with early-stage lower-risk breast cancer." (PMID 35386705, 2022). "Both CK5 and CK6 expressions were linked to high grade, estrogen and progesterone receptor negativity, and “triple negativity” in breast cancer (p < 0.0001 each), grade/stage progression in urothelial cancer (p < 0.0001), and RAS mutations in colorectal cancer (p < 0.01)." (PMID 34559291, 2022). "In this study, we used real-world clinical data and gene expression datasets (ERBB2, ESR1, PGR) to provide examples of how g3mclass may help overcome the problems of over-/underdiagnosis and equivocal results in diagnostic tests for breast cancer." (PMID 36335194, 2022). "Triple negative breast cancer (TNBC) is a subset of breast cancer, which is deficient in the expression of estrogen receptor (ER), progesterone receptor (PR), and human epidermal growth factor receptor 2 (HER2); therefore, TNBC does not respond to hormonal and anti-HER2 antibody therapies." (PMID 36230821, 2022). "Moreover, a family history of breast cancer, estrogen receptor (ER) status, progesterone receptor (PR) status, and triiodothyronine levels are associated with the development of thyroid and breast tumors." (PMID 35873566, 2022). "After the ER/PgR expression level was adjusted for the 70-gene signature using multivariate Cox regression analysis, patients in the highly endocrine-responsive category were associated with good breast cancer-specific survival (hazard ratio = 0.16)." (PMID 34638491, 2021). "Furthermore, upregulation of distinct HSPs was associated with either estrogen receptor-positive, progesterone receptor-positive, or human epidermal growth factor receptor 2-positive breast cancers." (PMID 34692733, 2021). "This is supported by recent findings in breast cancer cell lines that different synthetic progestins cause many of the same cellular outcomes when signaling through the classical or nuclear progesterone receptor (PGR), but have seemingly distinct PGRMC1-dependent actions." (PMID 34885064, 2021). "There is an upregulation of lncRNA SNHG6 in high-grade and progesterone receptor-positive breast cancer tissues, which may be associated to breast cancer cell migration and epithelial-mesenchymal transition (EMT)." (PMID 34026654, 2021). "Moreover, estrogen-receptor (ER) and/or progesterone-receptor (PR) positive breast cancer was associated with BMI in all age groups, whereas hormone-receptor negative breast cancer was associated with BMI only in women aged 18-24 years." (PMID 34485137, 2021). "The loss of PgR expression in ERα(+) breast cancer may signify resistance to endocrine therapy and poorer outcomes." (PMID 34638241, 2021). "As concerns cathepsin D, its high levels are significantly associated with the ER-positive and PgR-positive status of breast cancer, which might be expected as cathepsin D expression is under oestrogen control in ER-positive breast carcinomas." (PMID 33916398, 2021). "Importantly, exogenous expression of PgR in breast cancer cells ensued growth inhibition in an MCF-7 cell line with a heterozygous loss of the PGR gene." (PMID 34638241, 2021). "Consequently, receptors such as ER, PGR and proliferation markers such as Ki67 have been used as breast cancer biomarkers to predict risk." (PMID 33397518, 2021). "Furthermore, the OGG1 and XRCC1 rs25487 polymorphisms were nominally associated with PgR, Her2 status and with sporadic breast cancer, respectively." (PMID 32192442, 2020). "Lastly, high compared to low post-diagnosis physical activity is also associated with a reduction in risk of breast cancer-specific mortality in estrogen receptor-positive/progesterone receptor-positive (ER+/PR+), ER−/PR−, and triple-negative breast cancer (TNBC) patients." (PMID 33134306, 2020).
breast cancer (continued). "Furthermore, the HW phenotype was associated with increased risk of estrogen receptor/progesterone receptor-positive (ER+/PR+) breast cancer, with a 95% (OR = 1.95, 95% CI:1.21–3.13) increase." (PMID 32038481, 2019). "We investigated parity, breastfeeding, and breast cancer risk by hormone-receptor (estrogen (ER) and progesterone receptor (PR)) and molecular subtypes (luminal A, luminal B, HER2-enriched, and basal-like) in the Nurses’ Health Study (NHS; 1976–2012) and NHSII (1989–2013)." (PMID 30867002, 2019). "Triple-negative breast cancer (TNBC), one of the subtypes of breast cancer, accounts for 15–20% of all breast cancer cases, and is characterized by loss of the expression of the estrogen receptor (ER), progesterone receptor (PR), and human epidermal growth factor receptor 2 (HER2)." (PMID 30609732, 2019). "Stratified analysis by sex hormone status showed that dietary magnesium intake had a significant negative association with oestrogen receptor (ER)-positive (ER+) and progesterone receptor (PR)-positive (PR+) breast cancer risk in Model 3 (adjusted OR = 0.71; 95% CI = 0.53, 0.95)." (PMID 30962499, 2019). "We found that positive VDR expression in the nuclei and cytoplasm of breast cancer cells was associated with favorable tumor characteristics such as smaller size, lower grade, estrogen receptor positivity and progesterone receptor positivity, and lower expression of Ki67." (PMID 31358030, 2019). "The LUMINA study ‘A prospective cohort study evaluating risk of local recurrence following BCS and endocrine therapy in low risk luminal A breast cancer’ is also using IHC, including oestrogen receptor, progesterone receptor, HER2 and Ki67 status to determine luminal A subtype and direct treatment." (PMID 29331262, 2018). "Lower BPE in the contralateral breast in women with unilateral breast cancer might be associated to higher tumor grade and progesterone receptor negativity." (PMID 29351560, 2018). "We therefore determined expression of Notch3 and GATA-3 in tissue samples from breast cancer patients with immunohistochemistry (IHC) and explored their possible relationship with progesterone receptor (PR) and ER statuses, as well as their associations with other clinicopathologic features." (PMID 30100605, 2018). "In conclusion, BPE in the contralateral breast of patients with unilateral breast cancer in an intermediate and high-risk population might be negatively related to tumor grade and positively related to progesterone receptor status." (PMID 29351560, 2018). "The role of progesterone receptor (PGR) gene polymorphisms in breast cancer is still controversial." (PMID 29370776, 2018). "As the leading cause of cancer death in females, breast cancer is a heterogeneous disease that can be divided into three major subtypes: hormone (estrogen/progesterone) receptor-positive, HER2-positive, and triple-negative (estrogen, progesterone receptor and HER2-negative)." (PMID 28209156, 2017). "Few studies have addressed whether risk reduction pertains to specific breast cancer subtypes defined jointly by hormone receptor (estrogen and progesterone receptor) and human epidermal growth factor receptor 2 (HER2) expression." (PMID 28460643, 2017). "Our aim was to explore whether estrogen receptor (ER), progesterone receptor (PR), and Ki67 expression stratify risk of breast cancer in screened women with BBD." (PMID 28470951, 2017). "The SRA RNA is a non-coding RNA that strongly associated with breast cancer and participate in nuclear coactivation for several hormone-related systems, including the estrogen receptor, androgen receptor, progesterone receptor and thyroid hormone receptor." (PMID 26967566, 2016). "One study suggests that positive associations between IGF1 concentrations and breast cancer risk may be restricted to ER+ tumors, which may explain why stronger associations were observed for ER+ and/or PgR+ tumors in our study." (PMID 27376028, 2016).
breast cancer (continued). "Furthermore, the potential association between the expression of C1orf63 and known breast cancer biomarkers including estrogen receptor (ER), progesterone receptor (PR), and human epidermal growth factor receptor 2 (HER-2) were also examined." (PMID 26209438, 2015). "One report shows that higher expression of the progesterone receptor (PR) may be linked to the ability of MSCs to support growth of ERα-positive MCF-7 breast cancer cells under estrogen deficiency." (PMID 26515727, 2015). "A 2011 pooled study conducted among approximately 35,000, primarily Caucasian women revealed that the inverse association between obesity and premenopausal breast cancer may be restricted to women with ER+/progesterone receptor (PR)+ tumors." (PMID 26352264, 2015). "The association of high AMPKα expression with ER, PgR positive and non basal-like tumours may indicate differential expression of AMPKα in different breast cancer phenotypes and requires further verification." (PMID 25427448, 2014). "In breast cancer, miRNA expression profiling using microarray technology in association with some biopathological features such as estrogen receptor (ER), progesterone receptor (PR) and epidermal growth factor receptor 2 (HER2) status has been established as a useful tool to classify tumors." (PMID 24475217, 2014). "As increased activation of mTORC1 is known to mediate PgR expression and we demonstrated that loss of Rictor expression correlated with an ERα− breast cancer phenotype, we next sought to determine if there was a clinical correlation between Rictor or Raptor expression and loss of PgR expression." (PMID 25283550, 2014). "The number of cutaneous nevi and breast cancer risk by estrogen and progesterone receptor status." (PMID 24915186, 2014). "Approximately 80% of all breast cancers are susceptible for hormonal or antibody-based targeted therapy, based on the presence and/or abundance of the estrogen receptor alpha (ERα), progesterone receptor (PR) and/or the human epidermal growth factor receptor 2 (HER2)." (PMID 25280486, 2014). "Interestingly, mammary glands of IUGR animals fed a high-fat diet after puberty, show an increased phosphorylation of ERK-1/-2 and an induction of progesterone receptor at 4 months of age, which was associated with an increase in mammary tumor risk." (PMID 24955840, 2014). "However, in primary breast cancer, PgR expression is associated with differentiated, less aggressive tumours and a favourable prognosis." (PMID 24131622, 2013). "Relative risks (RR) for breast cancer and specific tumor characteristics (invasiveness, histological type, estrogen/progesterone receptor status, malignancy grade and stage) associated with this score were estimated using Cox regression controlling for potential confounders." (PMID 23390532, 2013). "However, few studies have investigated the black-white disparity in mortality risk stratified by breast cancer subtype, defined by estrogen receptor (ER), progesterone receptor (PR) and human epidermal growth factor receptor 2 (HER2) status." (PMID 23642215, 2013). "We did not observe an association between potential functional genetic polymorphisms in the estrogen pathway, SHBG rs6259, ESR1 rs2234693, CYP19 rs10046 and rs4775936, and UGT1A1 rs8175347, or the progesterone pathway, PGR rs1042838, with the risk of breast cancer." (PMID 23935996, 2013). "Previous epidemiological studies, including the Nurses’ Health Study, have reported stronger positive associations between birth weight and the development of breast cancer in estrogen receptor-positive (ER+) and/or progesterone receptor-positive (PR+) tumors compared to estrogen-independent tumors." (PMID 23061041, 2012). "Analysis by hormonal receptor status also showed a positive association between BMI and mortality risk among patients with ER + or PgR + tumors and with BMI ≥21.2 kg/m2 (p for trend: 0.020 and 0.031 for all-cause and breast cancer-specific death, respectively)." (PMID 22510365, 2012).
breast cancer (continued). "The aim of this study was to immunohistochemically detect the presence of estrogen receptor alpha (ERα), estrogen receptor beta (ERβ), and progesterone receptor (PR) and also to study the association between these markers in 29 cases of benign and malignant canine mammary tumors." (PMID 23738123, 2012). "Although the list of hypermethylated genes involved in the tumorigenesis of breast cancer has increased, much of the focus has remained on the estrogen receptor alpha (ESR1) and progesterone receptor (PGR) as these proteins have been implicated in breast cancer development and progression." (PMID 22220212, 2011). "In addition, univariate analyses revealed tumor stadium, nodal stage and progesterone receptor expressions as statistically significantly associated with OS in male breast cancer." (PMID 21816051, 2011). "Furthermore, HERmark positive breast cancers were significantly associated with invasive ductal carcinoma, high tumor grade, estrogen/progesterone receptor negativity, and expression of Ki67." (PMID 21151530, 2010). "Our findings indicate that methylation of EMILIN2, CIDE-A and FBLN2 are associated with positive estrogen and or progesterone receptor status, this may help in further refining breast cancers that are more likely to benefit from endocrine therapy." (PMID 20205715, 2010). "Progesterone receptor positivity decreased the risk of death from breast cancer." (PMID 21194468, 2010). "The murine mammary tumor induced by PyMT shares many features with poor-prognosis human breast cancer such as a high frequency of distant metastases, persistent expression of biomarkers, ErbB2/Neu and cyclin D1, and loss of estrogen and progesterone receptor expression." (PMID 20846433, 2010). "In breast cancer, two small retrospective studies has shown an association with elevated clusterin expression and large tumor size, estrogen and progesterone receptor status and with the progression from the primary carcinoma to metastatic carcinoma in lymph nodes in breast cancer." (PMID 20307318, 2010). "Prognostic factors, i.e., those that predict the risk of recurrence or death from breast cancer, include stage, number of positive axillary nodes, tumor size, lymphatic and vascular invasion, the estrogen-receptor (ER) and progesterone-receptor (PR) positivity, and HER2/neu gene amplification." (PMID 18990247, 2008). "Once this level is identified, surgeons, in early-stage luminal type breast cancer where surgical decisions are made, may anticipate an elevated risk of axillary metastasis based on reduced progesterone receptor levels, along with other established risk factors." (PMID 40283001, 2025). "However, limited studies have shown a relationship between PgR expression and tumor immunity in breast cancer; PgR expression is inversely associated with programmed death-ligand 1 (PD-L1) expression in epithelial cells or the stroma and the infiltration of CD8+ T and CD20+ B cells." (PMID 36721218, 2023). "This molecular subtype is characterized by a null or minimal expression of estrogen receptor, progesterone receptor, and human epidermal growth factor receptor 2 and is usually associated with poorer prognosis and higher recurrence rates compared to other molecular subtypes of breast cancer (BC)." (PMID 36835014, 2023). "Gallen Expert Consensus considered that the risk of breast cancer recurrence was mainly related to age, tumor size, histological grade, peritumor intravascular cancer emboli, and expression of the estrogen receptor (ER)/progesterone receptor (PR) and human epidermal growth factor receptor 2 (HER2)." (PMID 35619902, 2022). "It has been also reported that CAP2 is overexpressed in breast cancer, and it was significantly associated with progesterone receptor expression and decreased overall survival, thereby might be considered as a biomarker for the prediction of breast cancer prognosis and survival." (PMID 32042970, 2020).